PCGF6 (polycomb group ring finger 6)
Description:
Transcriptional repressor. May modulate the levels of histone H3K4Me3 by activating KDM5D histone demethylase. Component of a Polycomb group (PcG) multiprotein PRC1-like complex, a complex class required to maintain the transcriptionally repressive state of many genes, including Hox genes, throughout development. PcG PRC1 complex acts via chromatin remodeling and modification of histones; it mediates monoubiquitination of histone H2A 'Lys-119', rendering chromatin heritably changed in its expressibility. Within the PRC1-like complex, regulates RNF2 ubiquitin ligase activity.
Synonyms: MBLR; RNF134
Tractability: PROTAC: UniProt records ubiquitination sites on it; ubiquitination databases record sites on it.
Gene: Protein-coding gene on chromosome 10 (103,302,796 to 103,351,150, reverse strand). Ensembl gene ENSG00000156374.
Subcellular location: Nucleus
Pathways (Reactome):
Gene expression (Transcription): Transcriptional Regulation by E2F6
Gene Ontology:
Molecular function: protein binding
Biological process: chromatin remodeling; negative regulation of DNA-templated transcription; heterochromatin formation; regulation of transcription by RNA polymerase II; negative regulation of transcription by RNA polymerase II
Cellular component: nucleus; PcG protein complex; PRC1 complex; chromatin; nucleoplasm
Genetic constraint (gnomAD): Loss-of-function variants: 17 observed, 25.19 expected, observed/expected ratio (o/e) 0.67, 90% interval 0.46 to 1.01. The upper end of that interval is the gene's LOEUF score, 1.01, which puts it in group 4 of 6, group 1 being the genes least tolerant of losing a copy. Missense variants: 271 observed, 290.54 expected, observed/expected ratio (o/e) 0.93, 90% interval 0.84 to 1.03. Synonymous variants: 129 observed, 108 expected, observed/expected ratio (o/e) 1.19, 90% interval 1.03 to 1.38.
Homologues: Orthologues: chimpanzee PCGF6 (99% identical), macaque PCGF6 (99% identical), dog PCGF6 (95% identical), pig PCGF6 (94% identical), rabbit PCGF6 (91% identical), mouse Pcgf6 (88% identical), rat Pcgf6 (88% identical), guinea pig PCGF6 (70% identical), tropical clawed frog PCGF6 (56% identical), zebrafish pcgf6 (42% identical), rat Pcgf6l1 (30% identical), Drosophila melanogaster Psc (18% identical), and 1 more. Paralogues in human: PCGF1 (26% identical), BMI1 (24% identical), PCGF2 (24% identical), PCGF3 (24% identical), PCGF5 (23% identical), RING1 (16% identical), RNF2 (15% identical).
Diseases named in the same sentence as PCGF6 in open-access papers:
PCGF6 is named in the same sentence as 10 diseases in open-access papers, as found by Europe PMC text mining. Sharing a sentence is not in itself a finding about the gene and the disease. The quoted sentences say what the papers report.
glioma (1 paper, 2010). A benign or malignant brain and spinal cord tumor that arises from glial cells (astrocytes, oligodendrocytes, ependymal cells). "Other PRC1 members (CBX7, PCGF6) were selectively expressed in lower grade gliomas." (PMID 20920292, 2010).
lymphoma (1 paper, 2022). A malignant (clonal) proliferation of B- lymphocytes or T- lymphocytes which involves the lymph nodes, bone marrow and/or extranodal sites. "Unexpectedly, however, Pcgf6 loss shows no significant impact on transcriptional profiles, in neither pre-tumoral B-cells, nor lymphomas." (PMID 35422437, 2022).
non-small cell lung carcinoma (1 paper, 2021). A group of at least three distinct histological types of lung cancer, including non-small cell squamous cell carcinoma, adenocarcinoma, and large cell carcinoma. "We further confirmed decreased E2F6, L3MBTL2, and PCGF6 protein levels in MGA mutant human non-small cell lung cancer lines H2291 and Lou-NH-91 when compared to wild-type lines such as NCI-H1975, NCI-H23, and 91T." (PMID 34236315, 2021).
ovarian carcinoma (1 paper, 2011). A malignant neoplasm originating from the surface ovarian epithelium. "The upregulated genes encode for proteins associated with ovarian cancer metastasis [SERPINB2/PAI2], metabolic activities [IDI1, PMM2] and gene expression/transcription [PCGF6, ZNF267]." (PMID 22022533, 2011). "In HIO-80 cells, there was significant upregulation of genes encoding for proteins associated with ovarian cancer metastasis [SERPINB2/PAI2], metabolic activities [IDI1, PMM2] and gene expression/transcription [PCGF6, ZNF267]." (PMID 22022533, 2011).
prostate carcinoma (1 paper, 2024). A carcinoma that arises from epithelial cells of the prostate gland. "In agreement with our earlier observations, LISA-derived prediction showed that decreased DNA methylation in prostate cancer was associated with distinct chromatin remodeling enzymes, including BACH1 and PCGF6, in AA men." (PMID 38566104, 2024).
Stroke (1 paper, 2024). Sudden impairment of blood flow to a part of the brain due to occlusion or rupture of an artery to the brain. "Encouragingly, shRNAs against Dnmt3b, Pcgf6, and Mga were among those that are enriched after OGD treatment, consistent with the notion that DNA methylation and polycomb repressive complexes play important roles in stroke injury and neuroprotection." (PMID 38372724, 2024).
tumor (5 papers, 2020 to 2023). "Studies reported that PCGF6 was closely related to stem cell differentiation and various tumor progression." (PMID 36890610, 2023). "Altogether, these data unravel an unforeseen, Mga- and PRC1.6-independent tumor suppressor activity of Pcgf6." (PMID 35422437, 2022). "Unexpectedly, our data point to a distinct function of Pcgf6 in tumor suppression, independent from either Mga, PRC1.6, or transcriptional control." (PMID 35422437, 2022). "To begin to examine the role of ncPRC1.6 complex subunits in regulation of gene expression by MGA, we employed Crispr Cas9 to individually inactivate L3mbtl2, Pcgf6, or Mga in the mouse tumor derived KP cells." (PMID 34236315, 2021). "The link between ncPRC1.6 activity and the effects of MGA loss on specific gene expression was further investigated by comparing gene expression profiles of Crispr-mediated deletion of Mga with deletions of ncPRC1.6 subunits Pcgf6 and L3mbtl2 in KP tumor cells." (PMID 34236315, 2021). "To confirm whether PCGF6 is also involved in regulating hypomethylation of MAZ promoter in vivo, we tested the level of methylation in xenograft tumor tissue." (PMID 36890610, 2023).
cancer (4 papers, 2016 to 2023). A tumor composed of atypical neoplastic, often pleomorphic cells that invade other tissues. "Lee JH et al30 have shown that driver mutations in Pcgf6 enhance cancer cell migration, prompt metastasis, and may act by activating epithelial‐to‐mesenchymal transition." (PMID 31769218, 2020). "Recent studies have revealed that the PCGF family of proteins (PCGF1 (Nspc1), PCGF2 (Mel-18), PCGF3, PCGF4 (Bmi1), PCGF5 and PCGF6 is robustly elevated in diverse human cancers and promotes cancer progression." (PMID 34148069, 2021). "We identify driver mutations in ADPGK, NUP93, PCGF6, PKP2 and SLC22A5, which are verified to enhance cancer cell migration and prompt metastasis with in vitro experiments." (PMID 27625789, 2016). "All of the results suggest that MTs of ADPGK, PCGF6, PKP2, NUP93 and SLC22A5 can be the driver mutations controlling the cancer metastasis via affecting the EMT pathways where Snail, Claudin-1 or ZEB1 is involved." (PMID 27625789, 2016). "Interestingly, very recent studies showed that MGA, L3MBTL2 and PCGF6 are also destabilized upon USP7 inactivation in human cancer cell lines, indicating conserved USP7 function through mammalian evolution." (PMID 36772830, 2023).
PCGF6 also shares sentences with these, for which no sentence is quoted: brain tumor (1 paper); influenza infection (1).